TNF (tumor necrosis factor)
Diseases named in the same sentence as TNF in open-access papers (continued):
Sharing a sentence is not in itself a finding about the gene and the disease.
Cognitive impairment (continued). "Various proinflammatory cytokines, such as tumor necrosis factor alpha, maintain a state of chronic neuroinflammation, resulting in postoperative cognitive impairment and postoperative delirium." (PMID 34945858, 2021). "Surgical trauma will stimulate the peripheral immune system to release inflammatory factors such as TNF -α, resulting in cognitive impairment." (PMID 33787575, 2021). "TNF-α and IL-1β expression were positively correlated with cognitive impairment-like behaviors and Prevotellaceae and Bacteroidales populations in the gut microbiota." (PMID 34579150, 2021). "In AD, the levels of certain cytokines such as IL-1β and TNF-α (tumor-necrosis factor alpha) increase after the accumulation of Aβ but before the onset of cognitive impairment, suggesting that neuroinflammation contributes to AD pathogenesis early on." (PMID 33847763, 2021). "For instance, TNF-α expression-suppressing Lactobacillus mucosae NK41 alleviates Escherichia coli-induced cognitive impairment with gut inflammation in mice." (PMID 34667205, 2021). "In turn, cognitive impairment seems to correlate with peripheral levels of IL-1β, IL-4, IL-6 and IL-12, and considering only the AChR population, also with peripheral levels of TNF-α." (PMID 34501305, 2021). "Findings have demonstrated relationships between TNF-α and cognitive impairment and dementia, incidence of cardiovascular events, insulin resistance, frailty, and mortality." (PMID 34489672, 2021). "Activated microglia release proinflammatory cytokines (NO, IL-6, and TNF-α), inducing cognitive impairment and neuroinflammation." (PMID 34539802, 2021). "TNF-β levels were lower in participants with cognitive impairment, which is slightly surprising given its functional proximity to TNF-α and sTNF receptors." (PMID 36043690, 2021). "High fat diet (HFD) rodents showed cognitive impairment with elevated Interleukin-1β (IL-1β) and tumor necrosis factor α (TNFα) in the hippocampus." (PMID 34108878, 2021). "The role of inflammatory cytokines, especially TNF-α, IL-1β, IL-6, and IL-8, is well-established in neurodegeneration and cognitive deficits." (PMID 34103066, 2021). "In many studies, elevated levels of TNFα have been observed in elderly people with cognitive impairment." (PMID 33808526, 2021). "For instance, IL-1β up-regulation potentiates neurodegeneration induced by dopaminergic signalling, whereas excessive secretion of TNF-α contributes to cognitive impairment." (PMID 33557113, 2021). "Previous evidence has identified an increasing number of proinflammatory molecules involved in the cognitive impairment of AD, such as interleukin (IL)-6, tumor necrosis factor-alpha (TNFa), and the inflammasome complex (NLPR3)." (PMID 34829716, 2021). "Further, miR-485-3p ASO reduced the secretion of proinflammatory cytokines, including IL-1β and TNF-α, and eventually relieved cognitive impairment." (PMID 34884940, 2021). "The release of proinflammatory cytokines, such as TNF-α and IL-1β, has been reported as a critical factor in the development of cognitive deficits." (PMID 32655313, 2020). "It has been demonstrated that overexpression of TNF signaling enhances Aβ-induced pathology and learning and memory deficits, while TNF inhibition reduces cognitive impairment." (PMID 32977412, 2020). "Previous experiments showed that the LPS-treatment cognitive impairment mice model enhanced the secretion of IL-1β, IL-6, and TNF-α and the expression of iNOS and COX-2 with increased NO production." (PMID 32796824, 2020). "The low expression of TNF-α and IL-1β with the use of antibodies is thought to prevent neuronal damage and is expected to prevent the occurrence of Alzheimer’s disease or other cognitive disorders." (PMID 34367622, 2020). "Pro-inflammatory cytokines such as interleukins (ILs) and tumor necrosis factor (TNF)-α contribute to the nuclear factor-κB (NF-κB) dependent signalling pathway, which causes cognitive impairment." (PMID 32997222, 2020).
Cognitive impairment (continued). "According to Qi and collaborators, the NKT treatment reduced the levels of TNF-α, IL-1β, and IL-6 in models of cognitive impairment and dementia in rats, corroborating the data from our pleurisy model." (PMID 32392744, 2020). "Increased release of proinflammatory cytokines, including IL-1β and TNF-α, has been reported in the hippocampus of rodents after prolonged seizures, and contributes to cognitive impairment." (PMID 33161894, 2020). "In pathological conditions, microglia release large amounts of TNF-α that represents a critical mediator of neuronal dysfunction and cognitive impairment consequent to chronic neuroinflammation (Olmos and Lladó, 2014)." (PMID 33343293, 2020). "There is meta-analytical evidence that regular physical exercise can reduce inflammation-related biomarkers (e.g., CRP, TNF-α) in middle-aged and older adults, these benefits being also present in individuals with cognitive impairment." (PMID 32296418, 2020). "Melatonin and rapamycin significantly ameliorated the isoflurane-induced cognitive impairment and also led to a decrease in the melatonin levels as well as the expression levels of TNF-α, IL-1β, IL-6, and p-mTOR in the hippocampus." (PMID 31803045, 2019). "Our results suggest that AC significantly inhibited the cognitive deficits caused by SPS via increased expression of pro-inflammatory cytokines, including tumor necrosis factor-α and interleukin-6, in the rat brain." (PMID 30621666, 2019). "Ischemia is known to increase the deleterious effect of Aβ production for synaptic impairment by induction of IL-1β and TNF-α of microglia, contributing to early cognitive impairment in Alzheimer's disease." (PMID 30911291, 2019). "In the present study, inhibiting mast cell degranulation by the mast cell stabilizer cromolyn limited microglia activation and release of TNF-α and IL-6, and alleviated LPS-induced cognitive impairment." (PMID 31130850, 2019). "Belarbi and colleagues reversed chronic neuroinflammation induced cognitive impairment during novel place recognition and spatial learning in rats by treatment with a tumor necrosis factor protein synthesis inhibitor." (PMID 30975083, 2019). "Expression of IL-6, IL-8, and TNF-α in the two groups was reduced significantly with variation of the clinical scales of cognitive impairment." (PMID 29853963, 2018). "A similar study using a weight-drop injury model indicated a single systemic injection of TNF-α synthesis inhibitor 3,6′-dithiothalidomide (DT) prevented injury-induced increases in TNF-α and ameliorated neuronal loss and cognitive impairments in the mouse." (PMID 29789012, 2018). "Studies have shown that chemotherapy-induced neuroinflammation, including increases in TNF-α, are correlated with changes in myelination and cognitive impairment." (PMID 30100992, 2018). "In summary, our results propose that release of cytokines such as IL-1β, IL-6 and TNF-α and also MDA as lipid peroxidation index in brain tissue following TBI cause cognitive impairment and LTP insufficiencies." (PMID 30524680, 2018). "Synaptic deficits correlate closely to cognitive impairment in AD and TNFα inhibitors have been shown to rescue cognitive impairments in APP mouse models." (PMID 30135948, 2018). "Single studies suggest the role of C-reactive protein (CRP), interleukin (IL)-1 receptor antagonist, IL-6, and tumor necrosis factor-α (TNF-α) with its receptors in the development of cognitive impairment in bipolar disorder as summarized in reviews." (PMID 30349492, 2018). "PKR is increased in cerebrospinal fluid from patients with AD and mild cognitive impairment and can induce the activation of pro-inflammatory pathways leading to TNFα and IL1-β production." (PMID 28982375, 2017). "To understand the underlying mechanism how COX2 contributes cognitive deficits in the CUMS-treated rats, we assayed the levels of inflammatory biomarkers, including TNF-α, prostaglandins E2 (PGE2) and IL-6." (PMID 28415673, 2017).
Cognitive impairment (continued). "Similar to SNL, in mice underwent the combinative CA3 injections of ANA-12 and TNF-α (group 4), we detected the nociceptive, depressive, anxiety and cognitive deficits." (PMID 28931876, 2017). "High levels of neuroinflammatory cytokines, such as interleukin (IL)-1β, IL-6, and tumor necrosis factor (TNF)-α play a pivotal role in surgery-induced cognitive deficits." (PMID 28806788, 2017). "Increasing SIRT3 and decreasing CypD can attenuate cognitive impairment and neuroapoptosis, and protect the integrity of mitochondrial membrane from damage and restore the protein expressions of IL-6, TNF-α, and caspase-3." (PMID 28236057, 2017). "Anti-TNF-a has been also suggested as a potential treatment against cognitive impairment in Alzheimers disease." (PMID 27853420, 2016). "So reduction of elevated TNF-α and IL-1β can restore neuronal function and reverse cognitive deficits post TBI." (PMID 26818584, 2016). "Since synaptic dysfunction is ultimately responsible for cognitive impairments in AD, the effect TNFα has on synaptic integrity is crucial to understanding disease pathogenesis." (PMID 27672476, 2016). "In particular, genomic studies have further revealed a significant association between TNFα polymorphisms and AD and TNF signaling has been associated with conversion to dementia in patients with mild cognitive impairment (MCI)." (PMID 27672476, 2016). "Studies conducted in rats pretreated with the Aβ peptide found that WIN prevented cognitive impairment, glial activation and neuronal loss, and also reduced COX-2, iNOS and TNF-α levels." (PMID 25874692, 2015). "Inhibiting such an elevation in brain TNF-α in this model allowed the evaluation of the role of this transient TNF-α rise in neuronal cell loss, neuroinflammation, and cognitive deficits known to accompany mTBI." (PMID 25879458, 2015). "This study implicates TNF-α in the delayed neuronal cell death and gliosis that occurs within the brain following mTBI, which leads to cognitive deficits." (PMID 25879458, 2015). "In fact, recent data from our laboratory have shown that nephrectomy-induced cognitive impairment in rats seems to be related to an increase in GCs levels in cerebrospinal fluid (CSF) and TNF-α/IL-10 ratio compared to the Sham group." (PMID 26647069, 2015). "The inhibition of TNF-α synthesis blocked the mTBI-induced rise in brain TNF-α and protected against neuronal loss and cognitive deficits with a therapeutic window of 12 h." (PMID 25879458, 2015). "Together these results extend the work of Baratz and colleagues and define a therapeutic window of up to 12 h post mTBI to mitigate cognitive deficits by lowering TNF-α generation, as well as documenting the time course of TNF-α elevation." (PMID 25879458, 2015). "Treatment of anti-inflammation drug and blocking the signals of TNF-α and IL-1β all effectively decreased the cognitive impairment induced by surgery." (PMID 25198176, 2014). "Knockout of IFN-γ receptor reduced gliosis and amyloid plaques, and blockade of TNF-α reduced Aβ-induced cognitive impairments." (PMID 24656052, 2014). "Weak to moderate correlations were observed between IL-1β, IL-6, TNF-α levels, and different degrees of cognitive impairment." (PMID 24339912, 2013). "In a model of peripheral surgery-induced cognitive impairment, the memory dysfunction elicited following tibial fracture was shown to be both TNF-α and IL-1β-dependent." (PMID 23840908, 2013). "Our data demonstrate that the TNF-α synthesis inhibitor DT can significantly reverse hippocampus-dependent cognitive deficits induced by chronic neuroinflammation." (PMID 22277195, 2012). "Studies in subjects with mild cognitive impairment (MCI) that progress to develop AD suggest that increased CSF TNF-α levels are an early event, and their rise correlates with disease progression." (PMID 22642825, 2012).
Cognitive impairment (continued). "Herein we were able to demonstrate that the blood-brain barrier permeant TNF-α lowering agent, DT, effectively rescued hippocampus-dependent cognitive impairment induced by chronic neuroinflammation." (PMID 22277195, 2012). "The present study demonstrates that inhibition of TNF-α synthesis by 3,6'-dithiothalidomide reverses hippocampus-dependent cognitive deficits induced by chronic neuroinflammation." (PMID 22277195, 2012). "3,6′-DT was shown to be effective in ameliorating the TNFα increase and cognitive impairment resulting from a mild traumatic brain injury in mice." (PMID 22632257, 2012). "Herein, to further define the role of TNF-α in neuroinflammation, neuronal dysfunction and cognitive impairment, we utilized a TNF-α synthesis-lowering agent, 3,6′-dithiothalidomide, developed within our laboratory." (PMID 22642825, 2012). "Taken together, our data support that TNF-α is a critical mediator of chronic neuroinflammation-induced neuronal dysfunction and cognitive impairment." (PMID 22277195, 2012). "Thus, inflammatory cytokines IL-6, IL-1β, IL-13, and TNFα are elevated at this longer phase and are related to cognitive deficits and/or post-acute sequelae." (PMID 41516418, 2026). "In addition to anti-TNF-α, the effects of other types of drugs used to treat RA and cognitive impairment have also been evaluated." (PMID 40291023, 2025). "The results of this study suggest that TNF-α may be a strong predictor of cognitive impairments in middle-aged women." (PMID 40137151, 2025). "The cognitive deficit could also be aggravated by high brain exposure to pro-inflammatory cytokines, including IL-1β, IL-6, and TNF-α." (PMID 39777720, 2025). "Additionally, vitamin D supplementation ameliorated cognitive impairment and altered neurodegenerative (Aβ1-40, Aβ1-42, p-Tau, and Neprilysin) and inflammatory markers (IL-6, IL-1β, TNF-α, and NF-κβ) in the scopolamine-induced rat model." (PMID 41473190, 2025). "Similarly, chronic sleep restriction in mice increases neuroinflammation via pro-inflammatory cytokines (e.g., TNF-α, IL-6), contributing to cognitive deficits." (PMID 40958991, 2025). "Furthermore, the main cytokines, including interleukin-1β, tumor necrosis factor-α, and interleukin-6, and the activation of microglia and astrocytes lead to the disruption of the blood–brain barrier and to cognitive impairment." (PMID 41470817, 2025). "Furthermore, studies have demonstrated that pharmacological suppression of TNFα can minimize cognitive deficits." (PMID 40486726, 2025). "Moreover, subjects with cognitive impairment exhibited higher cytokine levels (both IL-1β and TNF-α) compared with subjects with normal cognition." (PMID 41149360, 2025). "Andrographolide (10 mg/kg, ip, 4 weeks) improved CCH-induced cognitive deficits and hippocampal apoptosis, inhibited astrocyte activation and decreased the expression of TNF-α, IL-1β caspase-3 in the hippocampus, while alleviated 2VO-induced decreases in the expression of BDNF and TrkB." (PMID 41230091, 2025). "Our study aligns with prior research, demonstrating that aerobic exercise suppresses the activation of M1 phenotype microglia in the hippocampus of mice with AS-induced cognitive impairment and reduces the expression of inflammatory cytokines IL-6, TNF-α, and IL-1β." (PMID 40556958, 2025). "Instead, the wild-type IGF-1 allele and non-wild type TNF-alpha allele were closely associated with cognitive impairment outcomes." (PMID 39061961, 2024). "Raised IL-6 and TNFα levels appear central to PASC/long COVID and complications, such as the increased risk of cardiovascular events, persist long after the acute infection, as does the neuroinflammation and associated cognitive deficits (“brain fog”)." (PMID 39000027, 2024).
Cognitive impairment (continued). "Preclinical and clinical studies have both shown that cognitive impairment induced by AD is accompanied by elevated levels of pro-inflammatory cytokines including interleukin-1 beta (IL-1β), IL-6, and tumor necrosis factor-alpha (TNF-α)." (PMID 38231482, 2024). "While our analyses focus on TNF-α as a key proinflammatory cytokine linked to the development and persistence of MDD, we also recognize the involvement of other inflammatory markers in depressive symptoms, including cognitive impairment." (PMID 38693319, 2024). "In addition, the study revealed significant cognitive impairment and greater deposition of Aβ deposits, as well as higher levels of pro-inflammatory cytokines, such as IL-1β and TNF-α, in their brains, compared to control mice." (PMID 39064809, 2024). "TNF-α is considered an inflammatory substrate for cognitive impairment in the early clinical stages of dementia, and studies have found that TNF-α-targeted therapies may be a biologically feasible way to maintain cognitive ability." (PMID 39376966, 2024). "Indeed, inflammatory cytokines, such as interleukin 1-β (IL-1β), interleukin-6 (IL-6), and tumor necrosis factor-alpha (TNF-α), are increased in AD and mild cognitive impairment (MCI) patients." (PMID 39057049, 2024). "In addition, sleep deprivation significantly elevated the levels of proinflammatory cytokines including IL‐1β, IL‐6, and TNF‐α in the hippocampus and resulted in cognitive impairment during the novel object recognition test." (PMID 38688894, 2024). "Notably, high TNF-alpha disrupts zinc homeostasis, leading to reduced synaptic activity and cognitive impairment, potentially explaining the behavioural alterations in BLCO-fed rats as shown in the results of this study." (PMID 39734606, 2024). "Interestingly, lower serum TNF-α concentrations have been determined in patients with mild cognitive impairment." (PMID 38392998, 2024). "This may be associated with hippocampal structural damage and elevated levels of IL-1β, IL-6, and TNF-α in the hippocampus, which leads to blood–brain barrier rupture and cognitive impairment." (PMID 40017811, 2024). "RUNX1 belongs to master regulators for the age-dependent microglia module and increases the level of G9a through histone lysine methylation, leading to the increase of neuroinflammatory markers such as interleukin-6, tumor necrosis factor-α and then cognitive impairment in rats." (PMID 37187578, 2023). "Another study revealed that the copresence of elevated blood TNF-α/IL-10 levels and mild cognitive impairment could predict early conversion of idiopathic rapid-eye-movement sleep behavior disorders into neurodegenerative synucleinopathies." (PMID 36897204, 2023). "However, in support of our observations, heightened levels of IL-1β and TNF-α have been found within mdx murine brains, who also displayed cognitive impairment similar to those in DMD patients." (PMID 37108685, 2023). "It is generally acknowledged that neuroinflammation plays an important role in the pathogenesis of Alzheimer’s disease and there are more inflammatory markers (TNFα, IL-1β, IL-6, IL-10) in patients with AD and mild cognitive impairment (MCI) than in healthy controls." (PMID 37081917, 2023). "In rodent models of cognitive impairment in diabetic rats and pentylenetetrazol-induced experimental epilepsy, meloxicam showed notable neuroprotection and rescued the behavioral deficits by dampening TNF-α and interleukins together with COX-2/PGE2 pathway." (PMID 37375795, 2023). "Moreover, microglial activation and production of proinflammatory cytokines and neurotoxic mediators, including interleukin-1 beta (IL-1β), tumor necrosis factor-alpha (TNF-ɑ), nitric oxide (NO), and ROS, can result in neuronal loss and cognitive deficits." (PMID 37081849, 2023). "Moreover, upregulation of proinflammatory cytokines, such as TNFα, can alter BDNF levels and promote neurodegeneration, which in turn can cause cognitive impairment." (PMID 37403256, 2023).